COL1A1 (collagen type I alpha 1 chain)
Diseases named in the same sentence as COL1A1 in open-access papers (continued):
Sharing a sentence is not in itself a finding about the gene and the disease.
breast tumor (11 papers, 2016 to 2024). "Our data suggest that COL1A1+ CAFs may block T‐cell immune infiltration through cell interaction in breast tumor microenvironment." (PMID 37021816, 2023). "Since metastases from ER-/PR- breast tumors are reportedly less likely to be skeletal compared to those from receptor-positive tumors, the precise importance of COL1A1/COL1A2 upregulation in TNBC remains unclear." (PMID 31139569, 2019). "Also, the collagen VI (COL6A1)/collagen I (COL1A1) mRNA ratio (COL6A1/COL1A1) was significantly higher in basal than luminal A breast tumours." (PMID 27725631, 2016). "To determine whether fibroblasts co-cultured with miR-510-5p overexpressing breast tumor epithelial cells are ‘activated’, we performed qPCR for collagen (COL1A1) and fibroblast specific protein (FSP1/S100A4), genes that are typically used as markers of cancer associated markers or CAFs." (PMID 37822942, 2023). "We found that the Col1a1 to Col1a2 ratio was 1.2 in mouse normal breast ECM and 2.6 in mouse breast tumor ECM, a more than two-fold increase in Col1a1 chain in the tumor ECM." (PMID 36547361, 2022). "In fact, in tumor extracellular matrix proteomic analysis from breast tumors, THBS2, followed by FBLN1 and COL1A1, have the highest correlation with collagen fiber alignment, an ECM trait predictive of shorter disease-free survival." (PMID 35159353, 2022). "COL10A1, COL1A1, and MFAP2 are constituents of the extracellular matrix remodeling, which is an important process in breast tumor invasion and tumor cell dissemination." (PMID 34149812, 2021). "Further analyses are needed of the 17(q22q25) duplication, which contains 482 genes including COL1A1, SOX9, RECQL5, and was described in specific subtypes of genomic changes in breast tumor and rhabdomyosarcoma." (PMID 29494553, 2018). "We used Oncomine to investigate the expressions of COL1A1 and FN1 in human breast tumor invasion and metastasis." (PMID 30237810, 2018). "Notably, COL1A1 and COL11A1 transcripts demonstrated high discrimination between normal breast tissue and breast tumors." (PMID 39716322, 2024). "Of note, the roles of COL1A1 and FN1 related to breast tumor invasion are still unclear." (PMID 30237810, 2018). "In a The Cancer Genome Atlas (TCGA) comparative study between normal breast tissue (n = 113) and breast tumors (n = 1109), COL11A1, COL12A1, COL1A1, COL1A2, COL5A1, and COL5A2 transcripts were upregulated in breast cancer and could discriminate between the two breast tissues." (PMID 39716322, 2024).
COVID-19 (11 papers, 2021 to 2025). A disease caused by infection with severe acute respiratory syndrome coronavirus 2. "All represented terms showed 5 common genes between our ORF-A549 cells and COVID-19 lung biopsies (COL1A1, COL4A3, COL4A4, COL5A1 and COL11A1)." (PMID 37545510, 2023). "Although the gene expression of COL1A1 assessed by real-time PCR was increased in the COVID-19 H7 (4.36 ± 2.9; n = 7) and compared to the control (1.01 ± 0.21; n = 3), we did not observe the statistical difference (p = 0.143), probably due to the low number of samples analysed." (PMID 37964271, 2023). "Upregulated genes in late COVID-19 mortality included those involved in pyroptosis (e.g., GZMA, CASP1) and fibrosis (COL1A1)." (PMID 35446789, 2022). "Specifically, signatures of plasma cells (IGHG3, IGKC, IGHM, JCHAIN, IGHG2, IGKV4-1, IGLV3-1, IGHA1), activated fibroblasts (COL1A1, COL1A2, COL3A1), inflammatory cytokines (CXCL9, CCL18) and complement factors (C1QB, C1QC) dominated the DE genes for the COVID-19 lung sections." (PMID 37858234, 2023).
glioblastoma (11 papers, 2009 to 2025). The most malignant astrocytic tumor (WHO grade IV). "Our functional enrichment of genes in patient tumors revealed that low expression of RND1 in glioblastoma induces an overexpression of focal adhesion proteins like extracellular matrix proteins (COL1A1 and LAMB1); integrins (ITGA5 and ITGB1); actin-binding proteins (FLNA; ACTN1) and vinculin." (PMID 30333910, 2018). "One study of patient microarray datasets found that six collagen genes (COL1A1, COL1A2, COL3A1, COL4A1, COL4A2, and COL5A2) play a role in immunosuppression and epithelial-mesenchymal transition in glioblastoma." (PMID 36276147, 2022). "The mechanism of tumor invasion and immune resistance involving COL6A3, COL1A1, COL1A2, LRRC15, IDO1, IL-6 and PTGS2 need to be further researched aiming to improve prognosis of aggressive glioblastoma." (PMID 33928021, 2021). "In addition, we also identified key genes, including MMP9, CD44, CDC42, COL1A1, COL1A2, CAMK2A, and CAMK2B, as potential target genes for diagnosing glioblastoma." (PMID 28191466, 2017). "For example, STCs exhibited, compared to STPs, the overexpression of several markers of the mesenchymal subtype of glioblastoma, such as COL1A1, COL1A2, COL5A1, IGFBP6, DCBLD2, many of which are also typically expressed by microglia or reactive astrocytes in glioblastoma microenvironment." (PMID 26188123, 2015).
Caffey disease (10 papers, 2009 to 2024). "A pathogenic missense variant in COL1A1 was previously reported in humans with infantile cortical hyperostosis, or Caffey disease, resembling canine CMO." (PMID 32033218, 2020). "Interestingly, the process was similar to Caffey disease (infantile cortical hyperostosis), which is caused by a single recurrent mutation (c.3040C> T) of the COL1A1 gene (also responsible for OI type I-IV)." (PMID 31244780, 2019). "Antenatal Caffey disease is very rare and although heterozygote COL1A1 mutations have been identified in some cases, genetic heterogeneity seems likely and TRPV6 may be a candidate worth investigation in unsolved cases." (PMID 30144375, 2018). "COL1A1 is closely related to Caffey disease and type I osteogenesis imperfecta, and its related pathways include the integrin pathway and collagen chain trimerization." (PMID 35093162, 2022).
gastric adenocarcinoma (10 papers, 2022 to 2025). "Mesothelioma and stomach adenocarcinoma displayed a higher expression profile for the COL1A1, COL5A1, ITGA4, and EMILIN1, in comparison to adrenocortical carcinoma and kidney renal papillary cell carcinoma." (PMID 35739492, 2022). "We also investigated the impact of CAF markers highly clustered with COL1A1 and COL5A1 in correlation analysis, namely THBS2, FAP, INHBA, S100A4, COL11A1, or MMP11, on the outcome of CAF infiltration in stomach adenocarcinoma." (PMID 35739492, 2022). "Despite that, adding TSPAN9 to the COL1A1, COL5A1, ITGA4, and EMILIN1 Cox model further increased the hazard ratio to 36.813 for CAF infiltration in stomach adenocarcinoma samples." (PMID 35739492, 2022). "With further analysis, we revealed COL1A1, COL5A1, ITGA4, EMILIN1, and TSPAN9 as a poor prognostic gene signature for CAF infiltration, with high specificity to stomach adenocarcinoma." (PMID 35739492, 2022). "All this data suggested COL1A1, COL5A1, ITGA4, EMILIN1, and TSPAN9 as a poor prognostic CAF signature with high specificity to stomach adenocarcinoma." (PMID 35739492, 2022). "Altogether, our bioinformatics analysis study identified six upregulated DEGs (ADAMTS2, COL10A1, COL1A1, COL1A2, COL8A1, and BGN) between gastric adenocarcinoma and normal tissues based on four different microarray datasets." (PMID 35726219, 2022). "In vitro, COL1A1 overexpression in HUVECs increased ANGPTL4, and co-culture with the gastric adenocarcinoma line MKN45 enhanced cancer cell invasion and proliferation, supporting a model in which ANGPTL4 from COL1A1+ ECs engages SDC4 on tumor cells to promote GC progression and spread." (PMID 41154806, 2025). "However, the addition of FN1 to the COL1A1, COL5A1, and ITG4 Cox regression model decreased the poor prognostic impact of CAF in stomach adenocarcinoma." (PMID 35739492, 2022). "Furthermore, studies have demonstrated the close relation between collagen genes and gastric adenocarcinoma, including COL10A1, COL1A1, COL1A2, and COL8A1." (PMID 35726219, 2022). "After that, we investigated whether the high expression of dual combinations of COL1A1, COL1A2, COL3A1, or COL5A1 exacerbates the outcome of CAF infiltration in stomach adenocarcinoma." (PMID 35739492, 2022). "Based on the comparative pan-cancer analysis of these key CAF markers and a comprehensive literature search we identified COL1A1, COL5A1, ITGA4, EMILIN1, and TSPAN9 as the signature genes, which potentiated the poor prognostic impact of CAF infiltration specifically in stomach adenocarcinoma." (PMID 35739492, 2022).
liver cancer (10 papers, 2020 to 2025). An epithelial or non-epithelial malignant neoplasm that arises from the liver. "There are some reports of the association between COL1A1 and fibrosis in HF based on the mouse model or in other diseases such as liver cancer." (PMID 31902369, 2020). "This analysis revealed that higher levels of COL1A1 and LOX, both of which are collagen‐related molecules, were associated with a worse long‐term prognosis in patients with primary liver cancer." (PMID 39703167, 2025). "Strikingly, the levels of COL1A1, ITGA2, and YAP are associated with morphological heterogeneity and poor overall survival of liver cancer patients." (PMID 35322024, 2022). "Kaplan-Meier analysis showed a clear association of high levels of COL1A1 and ITGA2 with poor prognosis of liver cancer patients (all P < 0.05)." (PMID 35322024, 2022). "Based on the analysis of 367 liver cancer patients from The Cancer Proteome Atlas (TCGA) database, the COL1A1 and COL1A2 signatures showed modest correlation with ITGA2 (R = 0.49, p < 2.2e-16, R = 0.51, p < 1.7e-12, Pearson’s correlation)." (PMID 35322024, 2022). "Importantly, DHA prevents and reverses fibrosis in a NASH mouse model and decreases expression of two out of three collagen encoding genes (COL1A1, COL1A2, COL4A1) that are upregulated in liver cancer and NASH." (PMID 37859621, 2023). "In liver cancer, there were relatively many studies on the function of COL1A1." (PMID 33828526, 2021). "We also find increased expression of myofibroblasts and fibrosis markers (PDGFRB, COL1A1, COL3A1, COL11A1) and early liver cancer markers (GPC3 and MUC1)." (PMID 41065540, 2025). "There was a positive correlation between COL1A1/ITGA2 and YAP/CTGF in liver cancer patient (R2 = 0.35, P < 1.1e-12, R2 = 0.49, P < 2.2e-15)." (PMID 35322024, 2022). "Firstly, we detected the expression level of ITGAV protein in clinical tissue samples from 5 patients with liver cancer, and found that the expression level of ITGAV in liver cancer tissues was positively correlated with the expression levels of CD68 (macrophage marker) and COL1A1 (CAFs marker)." (PMID 40018050, 2025). "Additionally, physical juxtaposition staining patterns were observed for COL1A1, ITGA2, and YAP in diversity-high tumor tissues, indicating an interaction between TAF and tumor cells mediated by COL1A1-ITGA2 and YAP-signals in diversity-high liver cancer patients." (PMID 35322024, 2022).
mesothelioma (10 papers, 2021 to 2024). A usually malignant and aggressive neoplasm of the mesothelium which is often associated with exposure to asbestos. "Amplification of the COL1A1 gene was detected in four mesothelioma samples." (PMID 37901248, 2023). "In addition, COL1A1 has already been described as a potential prognostic marker for mesothelioma, with a high expression correlated with a poorer overall survival." (PMID 35328227, 2022). "Interestingly, the addition of COL1A1 and COL5A1 to the CAF Cox model led to a decreased risk score for CAF infiltration in adrenocortical carcinoma, kidney renal papillary cell carcinoma, and mesothelioma." (PMID 35739492, 2022). "We found that the following four cancers showed an essential correlation between the prognosis of cancers and the expression of COL1A1, including LGG, KIRP, cutaneous melanoma (SKCM) and mesothelioma (MESO)." (PMID 35789341, 2022). "To predict possible players, we extracted the list of genes that correlate with the expression of COL1A1 and COL5A1 in adrenocortical carcinoma, kidney renal papillary cell carcinoma, and mesothelioma." (PMID 35739492, 2022).
glaucoma (9 papers, 2015 to 2025). Increased pressure in the eyeball due to obstruction of the outflow of aqueous humor. "Glaucomatous structural and functional damage has been linked to lower corneal thickness and hysteresis and COL1A1 mutations have been directly linked to glaucoma cases." (PMID 37074408, 2023). "In the present study we describe COL1A1 variants in four patients associated with different glaucoma forms: two presenting with PCG, two with JOAG and/or an early form of POAG." (PMID 27484908, 2016). "Altogether, these observations underline the importance of collagen genes, including COL1A1, in the eye and their putative role in glaucoma pathogenesis." (PMID 27484908, 2016). "Thus, we suggest including COL1A1 mutation screening in the genetic work-up of glaucoma cases and detailed ophthalmic examinations with fundus analysis in patients with OI." (PMID 27484908, 2016). "Additionally, genome wide association studies (GWAS) have shown that variants at collagen-related genes, including COL1A1, influence one of the main glaucoma risk factor such as central corneal thickness (CCT)." (PMID 27484908, 2016). "We suggest that the range of COL1A1 mutations presenting as either dominant or recessive differentially affect the collagen alpha-1(I) chain protein function resulting in a spectrum of connective tissue related phenotypes of varying severity including glaucoma features as recently proposed." (PMID 27484908, 2016). "The ECM gene expression levels were significantly lower in untreated normal LC cells than those of untreated glaucoma LC cells for all tested genes including Col1A1, αSMA, fibronectin, and vitronectin." (PMID 39273058, 2024). "In summary, the present data together with the recent literature support and expand the role of COL1A1 in the eye pathology suggesting a putative role in different forms of glaucoma." (PMID 27484908, 2016). "Undoubtedly, it is necessary widening the screening of COL1A1 in different, larger cohort of patients with glaucoma and additionally also OI to replicate and confirm these findings." (PMID 27484908, 2016). "Sanger sequencing of the complete coding region of COL1A1 was performed in a total of 26 further patients diagnosed with PCG or early onset glaucoma." (PMID 27484908, 2016). "Screening of COL1A1 in larger cohorts of patients with different forms of glaucoma would be now necessary to establish a detailed phenotype-genotype correlation." (PMID 27484908, 2016). "Remarkably, three studies on transgenic mice with targeted missense mutations in COL1A1 (not-affecting positions of amino acid Gly in the triple-helices) revealed a glaucoma-like phenotype supporting the causality of the variants identified in our patient." (PMID 27484908, 2016). "COL1A1 analysis of the complete coding region by Sanger sequencing was then carried out in an independent cohort of 24 German patients diagnosed with congenital/early onset glaucoma that were found negative for mutations in CYP1B1 and MYOC genes." (PMID 27484908, 2016). "Through literature review, several key glaucoma-related genes were identified, including MYOC, TBK1, COL1A1, COL1A2, FOXC1, LRP2, OPTN, and TEK." (PMID 40808675, 2025). "The overexpression of certain collagen genes (COL1A1 and COL1A2) in RCC suggests a role in extracellular matrix (ECM) remodeling, a critical factor in tumor metastasis, as well as in the structural changes observed in glaucoma." (PMID 40808675, 2025). "Interestingly, these glaucoma-related genes like MYOC, TBK1, COL1A1, COL1A2, FOXC1, LRP2, and TEK also showed significant differential expression in RCC tissues." (PMID 40808675, 2025). "Significantly high levels of Col1a1 mRNAs were found in conjunctival tissues of patients who had failed glaucoma surgeries compared to patients who had not previously undergone surgery." (PMID 40455034, 2025).
liver disease (9 papers, 2016 to 2026). "Interestingly, we found that HSC activation markers, such as Col1a1 mRNA, were reduced during ALD and metabolic dysfunction–associated steatotic liver disease resolution similarly in WD and WDA groups." (PMID 40288442, 2025). "The findings that hepatic LCN2 expression closely correlated with disease severity (i.e. ABIC and MELD scores), the degree of portal hypertension (i.e. levels of HVPG) and the expression of key fibrogenic genes (i.e. COL1A1, TIMP1) highly suggest a pathogenic role for LCN2 in AH." (PMID 32968110, 2020).
renal cell carcinoma (9 papers, 2014 to 2025). "In the GSE54460 renal cell carcinoma dataset, the expression level of COL1A1 was higher in the positive surgical margin group, and the P-value was less than 0.05, but the expression level of BGLAP was not correlated with the positive surgical margin." (PMID 37564213, 2023). "Concerning the COL1A1 gene, frequent promoter methylation was detected in renal cell carcinoma, and decreased expression was found in ovarian serous carcinoma." (PMID 24552139, 2014). "Our current results indicated that DUXAP8 and DUXAP9 may act as two key oncogenes in renal cell carcinoma through upregulation of COL1A1 and COL1A2 by competitively binding miR-29c-3p." (PMID 31409759, 2019). "These bioinformatic analytic findings indicate that pseudogene DUXAP8 and DUXAP9 may fuel onset and development of renal cell carcinoma by targeting COL1A1 and COL1A2 through competitively binding miR-29c-3p." (PMID 31409759, 2019). "Firstly, we determined the expression levels of five constituents (DUXAP8, DUXAP9, miR-29c-3p, COL1A1 and COL1A2) in 20 pairs of clinical cancer tissues and normal tissues of renal cell carcinoma." (PMID 31409759, 2019). "All these findings suggest that pseudogene DUXAP8/DUXAP9-miR-29c-3p-COL1A1/COL1A2 may be a critical signaling pathway in onset and progression of renal cell carcinoma." (PMID 31409759, 2019). "Taken together, amplification of pseudogenes DUXAP8 and DUXAP9 may lead to increase expression of COL1A1 and COL1A2 by competitively binding to miR-29c-3p, resulting in uncontrolled cell proliferation in renal cell carcinoma." (PMID 31409759, 2019).
cardiomyopathy (8 papers, 2019 to 2025). A disease of the heart muscle or myocardium proper. "Molecular evidence of cardiomyopathy, including inflammation marker (Tnd and Il6), fibrosis marker (Col1a1 and Col3a1), and hypertrophy marker (Nppa, Nppb, and Myh7), significantly increases when Rab7 was knocked out." (PMID 38837607, 2024). "Accordingly, RT-qPCR analysis confirmed that miR199a-5p reduced the expression of the cardiomyopathy marker genes nppa and Mhy7 as well as the genes expression of the collagen marker Col1a1, Col1a2, and Col3a1." (PMID 38956062, 2024). "Col15a1‐deficient mice exhibit non‐proto‐fibrillar protein deposits in the cardiac myocardium interstitium, along with an abnormal increase in the Col1a1/Col3a1 ratio, heightened myocardial stiffness, reduced elasticity, and decreased myocardial compliance, ultimately leading to cardiomyopathy." (PMID 39592912, 2025).
dentinogenesis imperfecta (8 papers, 2012 to 2025). Dentinogenesis imperfecta (DGI) is a hereditary dentin defect characterized by abnormal dentin structure resulting in abnormal tooth development. "Supported by Pallos etal, documenting a family with dentinogenesis imperfecta associated with a minimal bone phenotype caused by a COL1A1 mutation, we conclude that the spontaneous COL1A2 mutation caused the proband’s dentin defects." (PMID 23227268, 2012). "Dentinogenesis imperfecta is a common dental manifestation in OI, more frequently associated with COL1A2 mutations compared to COL1A1, due to the qualitative defects these mutations cause in collagen structure, a major component for bone and dentin." (PMID 40299462, 2025).